CCNE1 (cyclin E1)
Diseases named in the same sentence as CCNE1 in open-access papers (continued):
Sharing a sentence is not in itself a finding about the gene and the disease.
lung carcinoma (60 papers, 2008 to 2025). "The results in the public dataset confirmed the higher proportion of CCNE1(+) Cells in stage IIIA lung cancer, which were associated with metastasis and glycolysis." (PMID 41024301, 2025). "As one of key mRNAs in the ceRNA network of lung cancer, CCNE1 encodes cyclin E1 belonging to the highly conserved cyclin family." (PMID 38978021, 2024). "In cellular component associations with lung cancer, the targets were mainly found in the cell projection membrane, cell periphery, plasma membrane, catalytic complex, and cyclin E1-cyclin-dependent kinase 2 (CDK2) complex." (PMID 39518920, 2024). "Clinical studies have shown that high expression of E2F1 and CCNE1 are associated with poor prognosis in lung cancer patients." (PMID 33613291, 2021). "The major finding of our study is that miR-497 and miR-34a synergistically inhibit the expression of the same gene, CCNE1, and the function of its encoded protein, cyclin E1, thereby impeding the growth of lung cancer cells." (PMID 25909221, 2015). "The protein encoded by CCNE1, a newly identified cotarget for miR-34a and miR-497, plays a key role in regulating the growth of lung cancer cells, and its effect is mediated by the cooperative action of the two miRNAs." (PMID 25909221, 2015). "It has also been reported that miR-34a along with miR-497 inhibit lung cancer cell growth by cooperatively regulating the expression of cyclin E1." (PMID 40805201, 2025). "Overexpression of CCNE1 has been shown to be a poor prognostic indicator in lung cancer and to contribute to the growth and metastasis of the disease." (PMID 39944826, 2025). "The same downregulation of CCNE1 was also apparent in SIRT7 KD ARF-positive Calu-3 lung cancer cells and importantly in lungs of SIRT7-mutant mice, demonstrating the physiological relevance of this phenomenon." (PMID 38870055, 2024). "Exosomal miR-144-3p from bone marrow-derived mesenchymal stem cells suppresses the proliferation of lung cancer cells by downregulating cyclin E1 (CCNE1) and CCNE2." (PMID 36612314, 2023). "The overexpression of CCNE1 has been well documented in a variety of human tumors, including breast, ovarian, liver and lung cancers." (PMID 36964635, 2023). "Whereas, synergy effect in the combination of ATR inhibitor and WEE1 inhibitor is found in both high CCNE1-expressing osteosarcoma cell line and low CCNE1-expressing lung cancer cell lines." (PMID 37087441, 2023). "Meanwhile, ectopic expression of P65 also rescued S phase blockage and expression of cell cycle-related genes including CDK2, Cyclin D1 and Cyclin E1, in addition to NF-κB target genes including IL-1β, IL-6 and TNFα in lung cancer cells overexpressing ZNF24." (PMID 36457047, 2022). "The results showed that CCNE1, E2F1, ARHGAP11A, RUNX1T1 and FES were significantly associated with patient survival in lung cancer (n = 1925)." (PMID 33613291, 2021). "In vitro experiments showed that DMDD is an effective inhibitor of E2F1 and CCNE1 and leading to the suppression of proliferation, migration and clone formation in lung cancer cells." (PMID 33613291, 2021). "Cyclin E1 (CCNE1) is an important factor that regulates the proliferation of lung cancer cells into the S phase and G1 phase, which is reported to function in regulating the growth of lung cancer cells." (PMID 33683834, 2021). "Collectively, these results indicate that DMDD induces G1/S cell cycle arrest by regulating its potential targets E2F1 and CCNE1 in lung cancer cancer cells." (PMID 33613291, 2021). "Recent work in EGFR‐mutant lung cancer revealed that amplification of the CCNE1 gene can be found in patients with acquired resistance to EGFR inhibitors and specifically with acquired resistance to osimertinib." (PMID 32558295, 2020).
lung carcinoma (continued). "For example, Cbx7 has been identified to act as tumor suppressor in lung carcinoma by suppressing CCNE1 expression; conversely, it has been shown to act as an oncogene in gastric cancer by repressing p16 (INK4a)." (PMID 30357595, 2019). "The microarray analyses showed significant inverse correlation between SALL2 and CCNE1 mRNA expression in various cancers, including glioblastoma, lymphoma, cervix, pancreas, breast, colon, and lung cancer." (PMID 29689621, 2018). "CCNE1 is an important G1 phase-related gene, whose depletion inhibits lung cancer cells proliferation." (PMID 28423619, 2017). "MiR-497 retards lung cancer cell growth or invasion by targeting CCNE1, VEGFA, whereas miR-497 does so by targeting SSRP1 in HCC." (PMID 28624790, 2017). "In the present study, DDA1 was shown to be responsible for lung cancer cell G1/S transition and cell proliferation through the regulation of cyclin D1, cyclin D3, cyclin E1 and cyclin B1 expression." (PMID 28211159, 2017). "miR-107, as a paralog of miR-103, was identified in human nonsmall cell lung cancer, and the potential target CCNE1 was downregulated by transfection with miR-107." (PMID 26935418, 2016). "Our study extends the results of others by showing that miR-34a and miR-497 cotarget CCNE1 in lung cancer cells." (PMID 25909221, 2015). "Overexpression of miR-497 or miR-34a in A549, H460, and H1299 lung cancer cells by transfection with miR-497 or miR-34a mimics markedly reduced the levels of cyclin E1 protein." (PMID 25909221, 2015). "In conclusion, we showed that miR-497 and miR-34a act cooperatively to regulate certain aspects of tumorigenesis, including the growth of lung cancer cell lines, especially through their cooperative effect on the downregulation of cyclin E1 expression." (PMID 25909221, 2015). "Previous genome analysis using SNP Arrays also showed CDKN2A homozygous deletions and CCNE1 amplifications in lung cancers." (PMID 18549475, 2008). "We also verified that FGL1 is highly expressed in CCNE1(+) cells in these nine lung cancer samples using a public database, which could further support our findings." (PMID 41024301, 2025). "The CCNE1(+) Cells in the lung cancer and metastatic lymph nodes were identical." (PMID 41024301, 2025). "In addition to that, both triplets (SNHG1_mir-497_CCNE1 and PVT1_mir-497_CCNE1) showed a significant impact on survival rates of lung cancer patients." (PMID 38978021, 2024). "We performed the Kaplan–Meier analysis to determine whether the expression of LINC01116 and CCNE1 was related to the cancer‐specific survival rate in lung cancer patients." (PMID 39648148, 2024). "The data indicated that the CCNE1-high, CCNE1-high/EGR1-low, CCNE1-high/SCGB3A1-low and OTX1-high/CCNE1-high phenotypes, which might be involved in lung cancer malignancy, are related to poor prognosis in lung cancer." (PMID 36918558, 2023). "Moreover, it has been demonstrated that over-expression of miR-497 and miR-34a synergistically inhibited the expression of CCNE1, thereby inhibiting the growth of lung cancer cells." (PMID 36072388, 2022). "Therefore, CCNE1 and E2F1 have been confirmed to hold the potential to be diagnostic and prognostic markers in a variety of tumors, especially in lung cancer." (PMID 33613291, 2021). "Transgenic cyclin E1 triggers dysplasia and multiple pulmonary adenocarcinomas, and the overexpression of cyclin E1 was suggested to contribute to cancer development or tumorigenesis in various types of cancer, including breast, colon, and lung cancers." (PMID 25909221, 2015). "Based on previous data, we designed a study to test the hypothesis that cyclin E1 expression is coregulated by miR-497 and miR-34a in lung cancer." (PMID 25909221, 2015). "Increased expression of cyclin E1 is a useful marker of poor prognosis in lung cancer." (PMID 25909221, 2015). "Furthermore, our study revealed that MAP3K3 regulates the cell cycle through effects on CDC25A, CCND1/2 and CCNE1 regulation in lung cancer." (PMID 26088427, 2015).
lung carcinoma (continued). "Our data indicated that the tumor-suppressive miR-34a and miR-497 could co-inhibit cyclin E1, suggesting that cyclin E1 is a key target mediating the anti-tumor effect of miR-34a and miR-497 in lung cancer." (PMID 25909221, 2015). "DMDD may be used as an effective anti-lung cancer drugs by targeting CCNE1 and E2F1." (PMID 33613291, 2021). "In the ceRNA network of lung cancer, CCNE1 interacts with SNHG1 and PVT1 via mir-497, which is known to down-regulate cyclin E1 to inhibit the growth of lung cancer cells." (PMID 38978021, 2024). "Further investigation unveiled that METTL1/WDR4 accelerated lung cancer cell proliferation and migration by enhancing tRNA m7G modification and oncogenic mRNA translation, particularly CCND3 and CCNE1, the cell-cycle regulators." (PMID 36733406, 2023). "We found increased mRNA levels of p21 and a significant decrease in cell cycle-promoting proteins such as CDK2, CDK4, cyclin E1, and cyclin D1, suggesting a possible tumor-suppressing role of LCK in liver and lung cancers." (PMID 36430477, 2022). "In fact, previous clinical studies also showed that CCNE1 and E2F1 have a tumor promoting effect in many cancers including lung cancer." (PMID 33613291, 2021). "It is worth noting that CCNE1 and E2F1 were high expression in lung cancer and predictive of poor patient survival." (PMID 33613291, 2021). "Mechanistic studies showed that DMDD treatment induced G1/S cell cycle arrest by suppressing CCNE1, E2F1 and CDK2 and upregulating tumor suppressor gene p21 in lung cancer cells." (PMID 33613291, 2021). "We have identified that E2F1 and CCNE1 which are DMDD potential targets, were upregulated in lung cancer." (PMID 33613291, 2021). "Among the 60 potential therapeutic targets, cell cycle related genes CCNE1 and E2F1 were high expression and predictive of poor patient survival in lung cancer." (PMID 33613291, 2021). "Survival analysis showed that high expression of DMDD potential targets CCNE1 and E2F1 was significantly related to poor patient survival in lung cancer." (PMID 33613291, 2021). "PLK1 inhibition is lethal in K-RAS mutant cells as described in lung cancer, and in OC, synthetic lethality is produced with PLK1 inhibition and paclitaxel in CCNE1 amplified HGSC cells." (PMID 32268485, 2020). "In the present study in lung cancer, LINC00152 knockdown leads to reduced several cell growth-related proteins such as STAT3, p38α, CREB1, STAT1, c-MYC and CCNE1." (PMID 28592840, 2017). "In addition to cyclin B members, our results show that cyclin E members, such as CCNE1 and CCNE2, are also targeted by curcumol; CCNE1 plays a role in progression, cell proliferation, and cell cycle arrest of lung cancer cells." (PMID 35520289, 2022). "Cyclin E1 (CCNE1) is an important factor that can regulate the entry of proliferating cells into S and G1 phases, which is reported to play a role in regulating growth of lung cancer cells." (PMID 32102682, 2020). "IRF1 is downregulated in lung cancer, IPF and PAH datasets, probably because it represses the expression of genes involved in anti-proliferative response, such as BIRC5/survivin, CCNB1, CCNE1, CDK1, CDK2 and CDK4 and in immune response, such as FOXP3, IL4, ANXA2 and TLR4." (PMID 31867044, 2019). "Moreover, CBX7 was found to be significantly downregulated in human lung carcinoma tissues, which suggests that CBX7 functions as a tumor suppressor in these types of tissue by repressing cyclin E and CCNE1." (PMID 31211140, 2019). "Cordycepin could cause cell cycle arrest via the inhibition of the cyclin B/CDK complex at G2/M transition in human bladder cancer cell lines or down-regulate cyclin E1, cyclin A and CDK2 to induce S phase arrest in human lung cancer cells and gallbladder cancer cells." (PMID 33172093, 2020).
lung carcinoma (continued). "Besides, circCDR1as, one of the most frequently studied circRNAs, targets miR-7 in a manner dependent on NF-kB regulatory signaling, upregulates proliferation levels of EGFR, CCNE1, and PIK3CD, and thus induced superior proliferative, migratory, and invasive capabilities of lung cancer cells." (PMID 31534962, 2019). "In sharp contrast, CCNE1 expression did not change or even increased in ARF-negative SIRT7-depleted H226 and H322 lung cancer cells, respectively." (PMID 38870055, 2024). "The expression of CCNE1, CDKN1A (p21) and CDKN2A (p16) either did not appear to change or did not change in a similar direction in all 3 lung cancer cell lines as a function of BRG1 expression (data not shown)." (PMID 28105458, 2016). "In NSCLC, CCNE1 (Cyclin E1) focal amplification indicates hyperactivation of the Cyclin E–CDK2 axis and aligns with evidence that Cyclin E overexpression is a negative prognostic factor in lung cancer." (PMID 41303594, 2025).
serous ovarian cancer (48 papers, 2010 to 2025). "Previous studies have reported that 19q12 amplification mutations in CCNE1 are associated with tumor types, especially in uterine tumors, high-grade serous ovarian cancer, and gastroesophageal cancer." (PMID 39591374, 2024). "CCNE1 amplification is frequently present in high-grade serous ovarian cancer where it has a certain diagnostic value as it is generally mutually excluding with BRCA inactivation." (PMID 33947144, 2021). "A known driver is cyclin E1, which is particularly associated with polyploidy in high-grade serous ovarian cancer." (PMID 32823571, 2020). "Cyclin E1 drives polyploidy in high-grade serous ovarian cancer in association with CCNE1 gene amplification and is generally associated with genome doubling, but cyclin E2 has not been reported in this context." (PMID 32823571, 2020). "CCNE1 amplification occurs in approximately 20% of high-grade serous ovarian carcinomas (HGSCs) and is associated with primary treatment resistance and poor outcome in these tumors." (PMID 30665374, 2019). "Amplifications of cyclin E1 (CCNE1) are present in 25% of high-grade serous ovarian cancers and are associated with poor survival and impart resistance to CDK2 inhibitors." (PMID 26755558, 2016). "CDK2 inhibitors may also have clinical utility in subsets of cancers such as high-grade serous ovarian carcinomas, which harbor amplifications in the CCNE1 gene that encodes its partner cyclin E." (PMID 26320860, 2015). "Spatial transcriptomics confirmed the localization of CCNE1 in epithelial-rich regions and its correlation with adhesion- and motility-related genes in clear cell and high-grade serous ovarian carcinomas." (PMID 41331376, 2025). "CCNE1 amplification is most prevalent in high-grade serous ovarian carcinoma and serous endometrial carcinoma but is rare in cervical and low-grade tumors." (PMID 41331376, 2025). "CCNE1 plays an important oncogenic role in several tumors, especially high-stage serous ovarian cancer and endometrial cancer." (PMID 36964635, 2023). "CCNE1 amplification is a common alteration in high-grade serous ovarian cancer and occurs in 15–20% of these tumors." (PMID 37519629, 2023). "Here, we demonstrate that CCNE1-amplified high-grade serous ovarian cancer cells rely on homologous recombination to repair collapsed replication forks." (PMID 37519629, 2023). "A recent study suggest higher copy number of CCNE1 predicts higher sensitivities of high grade serous ovarian cancer to combination of WEE1 and ATR1." (PMID 37087441, 2023). "Prexasertib can also be combined with PD-L1 antibody LY3300054 (NCT03495323) to activate the cytotoxic T-cell in Cyclin E1 (CCNE1)-amplified high-grade serous ovarian-cancer (HGSOC) patients." (PMID 37373360, 2023). "CCNE1 amplification has been identified as a primary oncogenic driver in a subset of high-grade serous ovarian cancer." (PMID 36612212, 2022). "Interestingly, it has been observed that in High Grade Serous Ovarian Cancer (HGSOC) amplification of cyclin E1 (CCNE1) is associated with resistance to platinum-based chemotherapies, suggesting that targeting the cell cycle in these patients could represent an effective therapeutic approach." (PMID 34204543, 2021). "CCNE1 amplification has been identified as a primary oncogenic driver in a subset of high grade serous ovarian cancer that have an unmet clinical need due to resistance to standard of care and targeted chemotherapeutic agents." (PMID 32380689, 2020). "CCNE1 amplification has been identified as a primary oncogenic driver in a subset of high grade serous ovarian cancer that have an unmet clinical need." (PMID 32380689, 2020). "CCNE1 was reported to be repeatedly amplified and/or upregulated in high-grade serous ovarian cancer." (PMID 32102682, 2020). "CCNE1 amplification is associated with primary treatment resistance in high-grade serous ovarian carcinomas (HGSCs) and co-amplification of TPX2 with CCNE1 was common." (PMID 30665374, 2019).